IFT22 (intraflagellar transport 22)
Description:
Small GTPase-like component of the intraflagellar transport (IFT) complex B.
Synonyms: RABL5; FLJ14117; FLJ13225; DKFZp761N0823; FAP9; CFAP9
Tractability: PROTAC: ubiquitination databases record sites on it; its protein half-life has been measured.
Gene: Protein-coding gene on chromosome 7 (101,310,914 to 101,321,823, reverse strand). Ensembl gene ENSG00000128581.
Subcellular location: Cell projection, cilium
Subcellular location (Human Protein Atlas): Cytosol; Microtubules; Basal body; End piece; Flagellar centriole; Mid piece; Mitotic spindle; Primary cilium; Principal piece
Pathways (Reactome):
Organelle biogenesis and maintenance: Intraflagellar transport
Gene Ontology:
Biological process: cilium assembly; intraciliary anterograde transport; keratinocyte development
Cellular component: intraciliary transport particle A; intraciliary transport particle B; ciliary tip; cilium; centrosome; intraciliary transport particle
Genetic constraint (gnomAD): Loss-of-function variants: 11 observed, 20.59 expected, observed/expected ratio (o/e) 0.53, 90% interval 0.34 to 0.88. The upper end of that interval is the gene's LOEUF score, 0.88, which puts it in group 3 of 6, group 1 being the genes least tolerant of losing a copy. Missense variants: 227 observed, 239.97 expected, observed/expected ratio (o/e) 0.95, 90% interval 0.85 to 1.06. Synonymous variants: 67 observed, 84.87 expected, observed/expected ratio (o/e) 0.79, 90% interval 0.65 to 0.97.
Homologues: Orthologues: chimpanzee IFT22 (100% identical), macaque IFT22 (99% identical), pig IFT22 (91% identical), mouse Ift22 (90% identical), dog IFT22 (90% identical), guinea pig IFT22 (89% identical), rabbit IFT22 (80% identical), tropical clawed frog ift22 (66% identical), zebrafish ift22 (62% identical).
Diseases named in the same sentence as IFT22 in open-access papers:
IFT22 is named in the same sentence as 6 diseases in open-access papers, as found by Europe PMC text mining. Sharing a sentence is not in itself a finding about the gene and the disease. The quoted sentences say what the papers report.
ciliopathies (2 papers, 2015 to 2025). "The study found that SPAG6, TRAF3IP1, IFT22, and KIF3B showed lower correlations with ciliopathies, while IFT172, TTC21B, CEP290, ACTB, and DYNC1H1 were highly correlated." (PMID 40432967, 2025).
autosomal recessive polycystic kidney disease (1 paper, 2025). An inherited disorder characterized by the development of cysts affecting the collecting ducts. "The IFT22 gene is implicated in autosomal recessive polycystic kidney disease (ARPKD) and Bardet-Biedl syndrome (BBS)." (PMID 40572705, 2025).
IFT22 also shares sentences with these, for which no sentence is quoted: Bardet-Biedl syndrome (1 paper); breast carcinoma (1); genetic disease (1); prostate tumors (1).